PRKACB (protein kinase cAMP-activated catalytic subunit beta)
Diseases named in the same sentence as PRKACB in open-access papers (continued):
Sharing a sentence is not in itself a finding about the gene and the disease.
tumor (24 papers, 2014 to 2026). "Consistent with previous studies, protein kinase CAMP-activated catalytic subunit beta (PRKACB) had a significant discrepancy of expression in normal and tumor tissues and it was also associated with poor patient-free survival and overall survival." (PMID 35562390, 2022). "The results outlined that low expression of PRKACB in tumor tissues was considerably associated with poor disease-free survival (log rank P = 0.0025) and overall survival (log rank P = 0.0186) in patients with CRC." (PMID 32626531, 2020). "Interestingly, PRKACB is also associated with inhibiting the proliferation and invasion of tumor cells, making it a promising therapeutic target in combination with existing immunotherapies." (PMID 39835132, 2024). "In view of the findings of preceding studies, it was determined in the present study that FENDRR curtails persistent tumor growth by instigating the sinking of the DUSP4/CREB/PRKACB axis." (PMID 40630642, 2025). "Concurrently, relevant studies have clearly reported the promoting effect of DUSP4/CREB/PRKACB on tumor progression." (PMID 40630642, 2025). "circ-RAD18 was found to be highly expressed in patients with AML, promotes AML cell proliferation, and accelerates tumor progression via miR-206/protein kinase CAMP-activated catalytic subunit beta (PRKACB)." (PMID 35795049, 2022). "Consistent with our qRT-PCR results, ZNF292 and STMN1 staining were higher in tumor samples, while staining of PRKACB was lower in tumor." (PMID 33201835, 2020). "The study suggests that miR-384 serves as a tumor suppressor in PTC progression by directly targeting the 3′-UTR of PRKACB gene." (PMID 31998791, 2020). "Previous studies have confirmed that the c-MYC was directly activated by PRKACB, which then induced neoplasia 15,16." (PMID 32626531, 2020). "Our qRT-PCR analysis demonstrated that STMN1 and ZNF292 were overexpressed in tumor samples, while PRKACB expression was higher in paracancerous samples." (PMID 33201835, 2020). "The authors also demonstrated that PRKACB was a tumor suppressor gene through promoting tumor cells apoptosis and inhibiting tumor cells proliferation and invasion." (PMID 28415685, 2017). "The expression of C6orf120 and PRKACB was assessed by qPCR in pre-treatment tumor biopsies from EAC patients (n=30), who subsequently received neoadjuvant CRT." (PMID 28002789, 2017). "PRKACB (HR = 0.586), PPP2R5C (HR = 0.388), and MAPK3 (HR = 0.143) are associated with improved survival, suggesting their higher expression is protective against tumor progression." (PMID 39975150, 2025). "Thence, we can boldly speculate that PRKACB plays a synergistic role with these tumor suppressors in inhibiting tumor growth." (PMID 32626531, 2020). "On the contrary, oncogenes antagonize the tumor-suppressive effect of PRKACB." (PMID 32626531, 2020). "However, when we restored the expression of PRKACB gene in K1/miR-384 cells, the tumor size increased." (PMID 31998791, 2020). "Targeting the MAPK signal transduction pathway through the targeting of the FGF2, FGF9, MECOM, PLA2G4C and PRKACB might increase tumor responsiveness to irinotecan treatment." (PMID 28749961, 2017). "PRKACB expression was significantly lower in DGC tissues compared to IGC and adjacent non-tumor tissues." (PMID 41851075, 2026). "Mechanistically, FENDRR has been demonstrated to induce the sinking of the DUSP4/CREB/PRKACB signaling pathway and reverse the epithelial–mesenchymal transition (EMT) pathway, thereby inhibiting tumor growth." (PMID 40630642, 2025). "MiR‐302a‐3p serves as a tumor suppressor for non‐small‐cell lung cancer and HCC, and its targets include ACAT1 and PRKACB." (PMID 40761482, 2025). "Another interesting observation here is the presence of signaling by the VEGF pathway, which involved two upregulated genes (KDR, VEGFA) and three downregulated genes (NRP1, PRKACB, ROCK1) in G2 tumor AOIs compared to G1." (PMID 39245631, 2025).
tumor (continued). "Correlation analysis between the feature genes and immune cell signatures revealed that MAP2K1 and PRKACB are positively correlated with CD4+ T cells and immune score, both of which are crucial for anti-tumor immunity." (PMID 39835132, 2024). "AHR promotes immune evasion and tumor progression, influencing MAP2K1 and PRKACB, which regulate key pathways like MAPK and NF-κB signaling, respectively." (PMID 39835132, 2024). "To validate the regulation of PRKAR1A and PRKACB by miR-200c, we correlated mRNA expression of both PKA subunits to miR-200c expression in the NCI-60 panel of tumor cell lines." (PMID 26203557, 2015). "However, due to the small sample size of OS tumor tissues included in this study, we failed to observe the significant difference of PRKACB between tumor and adjacent normal tissues." (PMID 37293295, 2023). "In conclusion, targeting the MAPK signal transduction pathway through the targeting of FGF9, FGF2, MECOM, PRKACB and PLA2G4C might increase tumor responsiveness to irinotecan and improve patient survival thus being therapeutically and prognostic significant in CRC patients." (PMID 28749961, 2017). "Given that miR-17-5p expression is significantly lower in pre-treatment tumor biopsies from EAC patients who subsequently have a poor response to neoadjuvant CRT, we hypothesised that C6orf120 and PRKACB would consequently be upregulated in poor responder tumors." (PMID 28002789, 2017). "However, BMI, tumor stage, lymph node stage, metastasis stage, AJCC stage, lymphovascular invasion, perineural invasion, vascular invasion, race category, person neoplasm status were not significantly different in PRKACB expression (P> 0.05)." (PMID 32626531, 2020).
adenocarcinoma (1 paper, 2022). A common cancer characterized by the presence of malignant glandular cells. "The PFS of the patients with low PRKACB expression was longer than that of the patients with high PRKACB expression; which showed with non-responders in adenocarcinoma." (PMID 35135489, 2022).
neurodevelopmental disorder (1 paper, 2025). A behavioral and cognitive disorder with onset during the developmental period that involves impaired or aberrant development of intellectual, motor, or social functions. "Germline and mosaic variants of PRKACB are associated with congenital malformations and neurodevelopmental disorders." (PMID 41278641, 2025).
neurological diseases (1 paper, 2020). "Similarly, phosphorylation of PRKACB has also been found in neurological diseases." (PMID 32626531, 2020).
PRKACB also shares sentences with these, for which no sentence is quoted: Obesity (2 papers); acromegaly (1); acute myocardial infarction (1); adenoma (1); adrenocortical adenoma (1); adrenocortical tumors (1); atherosclerosis (1); autism spectrum disorder (1); bile duct tumors (1); biliary tract cancer (1); brain tumors (1); colon adenoma (1); colorectal adenocarcinoma (1); colorectal tumors (1); dilated cardiomyopathy (1); hearing loss (1); hyperinsulinism (1); infection (1); Insulin resistance (1); major depression (1); myopia (1); neurodegenerative disease (1); Oligodontia (1); osteoarthritis (1); papillary carcinoma (1); periventricular nodular heterotopia (1); primary immunodeficiency (1); rectal adenocarcinoma (1); renal cell carcinoma (1).